H19 (H19 imprinted maternally expressed transcript)
Diseases named in the same sentence as H19 in open-access papers (continued):
Sharing a sentence is not in itself a finding about the gene and the disease.
glioma (continued). "H19 By activating NF-kB signaling could confer TMZ resistance in glioma." (PMID 34178658, 2021). "In this study, we explored whether radiation-induced CREB1 directly activates H19 transcription, and then, the depletion of H19 reduced the radioresistance of glioma cells, aiming at providing a novel target for radiotherapeutic intervention against glioma." (PMID 34159190, 2021). "Furthermore, H19 could serve as a miRNA precursor and modulate glioma progression by generating miR-675, which could regulate the proliferation and migration of glioma cells by inhibiting the expression of CDK6." (PMID 31052326, 2019). "H19 could promote proliferation and invasion of glioma cells also by sponging of miR-152." (PMID 30217088, 2018). "Furthermore, serving as a miRNA precursor, H19 could modulate glioma progression by generating miR-675." (PMID 28293170, 2017). "In addition to miR-675, miR-29a is also a potential target for H19 in glioma angiogenesis." (PMID 28187439, 2017). "However, more function of H19 besides provide miR-675 in glioma need further investigation." (PMID 24466011, 2014). "For example, lncRNA H19 can act as a ceRNA through the miR-138/HIF-1α axis to promote the proliferation and invasion of glioma cells." (PMID 38730506, 2024). "H19, a hepatocyte growth factor (HGF) -induced lncRNA, has been shown to be highly expressed in a variety of tumors, including gliomas." (PMID 37228500, 2023). "Accordingly, the knockdown of lncRNA H19 resulted in miR-29a upregulation and the downregulation of its target, vasohibin 2 (VASH2), in ECs, ultimately leading to the inhibition of glioma-induced EC angiogenesis in vitro." (PMID 37443725, 2023). "In glioma, increased TMZ resistance, conferred by the upregulations of risky lncRNAs such as H19, MALAT1, PVT1, and SBF2-AS1, is likely to play a key role in the therapeutic efficacy of surgical resection plus drug treatment." (PMID 36819921, 2023). "This review compiles several differentially expressed lncRNAs in IDH-mutant and IDH-wildtype gliomas, and it has been shown that lncRNAs SBF2-AS1, PVT1, MALAT1, and H19 significantly contribute to the induction of TMZ resistance." (PMID 36819921, 2023). "For example, in cholangiocarcinoma cell lines (QBC939, sk-cha-1, and RBE) and glioma cell lines (U251 and ln229), both short-term and long-term oxidative stress induced by H2O2 or glucose upregulated the expression of H19 in cells." (PMID 36364766, 2022). "The T cell depletion-related prognostic model was developed based on seven prognostic genes (HSPB1, HOXD10, HOXA5, SEC61G, H19, ANXA2P2, HOXC10) in glioma." (PMID 36531217, 2022). "Consequently, H19 may be future target to the immunotherapy for glioma." (PMID 36246634, 2022). "Expression of many lncRNAs has been shown to be dysregulated in glioma, such as the up-regulation of NEAT1, HOTAIR, FOXM1-AS, H19, SOX2OT, and HCP5 expression and the down-regulation of GAS5, NBAT-1, and CASC2 expression." (PMID 35359381, 2022). "Furthermore, down-regulation of H19 could inhibit the malignant phenotype of glioma cells." (PMID 34796112, 2021). "The expression of H19 non-coding RNA is induced by c-Myc product, a member of the MYC proto-oncogene family, which promotes development of glioma." (PMID 34081618, 2021). "H19 stimulates the expression of stemness markers such as CD133, NANOG, OCT4, and SOX2 inducing the clone-forming ability of glioma and breast CSCs." (PMID 33799834, 2021). "In this study, the expression of H19, miR-200a, CDK6 and ZEB1 as well as their interaction in glioma have been investigated." (PMID 34796112, 2021). "For example, lncRNA H19, XIST, FOXD2-AS1, HOXC-AS2 act as molecular sponges for miRNAs to promote EMT-related genes and thus facilitate EMT, migration and invasion of glioma cells." (PMID 34880375, 2021). "In conclusion, our results revealed the interaction of H19, miR-200a and CDK6/ZEB1 in glioma cells, which can affect tumor progression." (PMID 34796112, 2021).
glioma (continued). "Therefore, H19 might play a crucial role in enhancing the radioresistance of glioma." (PMID 34159190, 2021). "It was demonstrated that some lncRNAs, such as H19, lnc-POU3F3, HULC, Xist, HOTAIR, SNHG15 and PVT1 are upregulated in angiogenesis of glioma." (PMID 34200145, 2021). "H19 is significantly upregulated in TMZ-resistant glioma, and H19 knockdown decreased the IC50 values for TMZ and increased rates of apoptosis in TMZ-resistant glioma cells by altering the expression of major drug resistance genes." (PMID 34316694, 2021). "Then multivariate analysis was performed, and it was found that among these factors, H19 (HR=1.71; 95% CI=1.37-2.13; P <0.0001) remained independently related to overall survival, suggesting that H19 could be an independent prognostic factor for glioma patients." (PMID 32081833, 2020). "Our analysis indicated that JAG1, PVT1, H19, and HAR1A were aberrantly expressed in IDH mutant gliomas and were core lncRNA genes in regulating the expression of protein-encoding gene in IDH mutant gliomas." (PMID 33329315, 2020). "They linked some previously glioma-associated lncRNAs, like H19, CRNDE, and HOTAIRM1, with recurrence, and also defined new lncRNAs, like AC016745.3, XLOC_001711, and RP11-128A17.1, which their lncRNA–mRNA co-expression analysis indicated might have critical roles in glioma recurrence." (PMID 32650527, 2020). "Another lncRNA H19 is processed from the H19-IGF2 loci, can be induced by c-myc and HIF1α, and is upregulated in glioma and other malignancies." (PMID 30644073, 2019). "Multiple lncRNAs have been reported to be involved in the initiation and progression of glioma, which include CRNDE, H19 and XIST, GAS, Malat1, Hotair, and SOX2ot." (PMID 31052326, 2019). "Together with H19 and HOTAIRM1, CRNDE was also found among lncRNAs upregulated in recurrent gliomas." (PMID 30217088, 2018). "Emerging evidences have indicated that lncRNAs are correlated with glioma drug resistance, such as XIST, MALAT1, CACSC2, and H19." (PMID 29552296, 2018). "Thus, LncRNA H19 could be increasingly recognized as a potential target for glioma treatment." (PMID 28293170, 2017). "H19 transcript can produce a miRNA (miR-675), which directly regulates CDH13 (Cadherin 13), thereby modulating glioma cell invasion." (PMID 29137410, 2017). "The expressions of H19, MALAT1 and POU3F3, for instance, were positively correlated with more malignant glioma phenotypes, and H19 also modulates glioma cell invasion." (PMID 26230711, 2015). "However, the role and function of lncRNA H19 in glioma development remain unclear." (PMID 24466011, 2014). "Another paper suggests that the role of H19 could depend on its ability to recruit and activate NF-κB signaling, which may represent a novel therapeutic target for TMZ-resistant gliomas." (PMID 41149459, 2025). "Furthermore, oxidative stress induces H19 expression and thus increases cell survival and viability by activating NF-κB signaling, which accompanies the acquisition of TMZ resistance by glioma cells." (PMID 36819921, 2023). "Previous studies have illustrated that lncRNA H19 activates the VEGF signaling pathway via sparing miR-138 to promote glioma angiogenesis, and that lncRNA BCYRN1 regulates the PTEN/AKT/p21 pathway to inhibit glioma tumorigenesis." (PMID 37934582, 2023). "Induced-H19 enhances activation of NF-κb signaling promoting expression of pivotal oncogenic genes such as Blc-2 and XIAP—which are upregulated in several human gliomas and to protect from apoptosis cellular." (PMID 35955440, 2022). "The results revealed that H19 expression was remarkably up-regulated in glioma tissues (GBM) compared to noncancerous controls (Tumor=163, Normal=207, p<0.05)." (PMID 34796112, 2021).
glioma (continued). "Furthermore, the biological effects of H19, miR-200a, CDK6 and ZEB1 in glioma tissues/cells were also elucidated in vivo and in vitro." (PMID 34796112, 2021). "H19 acts as a ceRNA on miR-138, which targets HIF-1α and modulates the expression of VEGF, thus promoting proliferation, migration, invasion, and angiogenesis in gliomas." (PMID 33980320, 2021). "In addition, lncRNA H19 induces the proliferation and EMT of several glioma cell lines and human glioma tissues by sponging miRNAs including miR-152 and miR-130a-3p." (PMID 34202078, 2021). "For example, H19 enhances Sox4 expression by sponging miR-130a-3p, which promotes EMT in glioma." (PMID 33028341, 2020). "In other studies, when the imprinting status of H19 and insulin-like growth factors 2 (IGF2) were manipulated, the development of brain tumors including meningiomas, medulloblastomas, and gliomas could be altered." (PMID 32434961, 2020). "Interestingly, genes involved in gliomas development (IGF2, H19, PHLDA2/TSSC3, TRIM3, SLC22A18) are located in the gene locus 11p15.5 of the beta hemoglobin chain." (PMID 32183175, 2020). "The knockdown of H19 suppressed tumorigenicity and stemness in U251 and U87MG glioma cells." (PMID 31052326, 2019). "Therefore, H19 seems to function also via H19/miR-675/CDH13 axis by deriving miR-675, suggesting H19 is a candidate for the future therapy of gliomas." (PMID 30217088, 2018). "H19, MALAT1 and HOXA11-AS down-regulates the expression of miR-140-5p in glioma." (PMID 30583549, 2018). "Moreover, as a precursor, H19 derived miR-675 and then regulated Cadherin 13 (CDH13) which is the directly target of miR-675, thereby modulating glioma cell invasion." (PMID 24466011, 2014). "Moreover, the novel feedback loop involving H19/miR-200a/CDK6 and ZEB1 could regulate the proliferation, invasion and migration of glioma cells." (PMID 34796112, 2021). "However, the detailed roles of H19 in tumor progression have not been fully understood, and its exact role in glioma has not been elucidated." (PMID 34796112, 2021). "Primary disease, age, cancer status, grade and radiation therapy had effects on the prognosis of patients with glioma, and radiation therapy had opposite therapeutic effects on LGG and GBM patients, suggesting that the expression of H19 could act as an indicator molecule." (PMID 32081833, 2020). "Besides, it was found that the copy number variations of H19 could notably affect the infiltration level of glioma immune cells, but could not affect the mRNA level of H19." (PMID 32081833, 2020). "However, radiotherapy could upregulate H19 expression, indicating that radiotherapy might not be suitable for patients with glioma." (PMID 32081833, 2020). "In contrast, there is no specific enrichment with a FOXM1 antibody at the promoters of H19, myoglobin and CCND1 3 which are genes non-expressed or imprinted in glioma cells (they serve as negative controls)." (PMID 34131149, 2021). "However, the biological effects of H19, miR-200a, CDK6 and ZEB1 as well as their interaction in glioma has not been elucidated." (PMID 34796112, 2021).
lung carcinoma (135 papers, 2007 to 2026). "H19 promotes lung cancer progression by modulating pathways associated with cell proliferation, invasion, and metastasis." (PMID 39201688, 2024). "Our research conclusively shows that β-elemene can counteract gefitinib resistance in lung cancer cells by suppressing autophagy linked to lncRNA H19 and halting the autophagy-driven degradation of EGFR." (PMID 38794196, 2024). "H19 plays an important role in embryonic development and tumorigenesis, and is associated with multiple cancers, such as lung cancer, bladder cancer, ovarian cancer and pancreatic cancer." (PMID 34976181, 2022). "Together, these studies demonstrated that H19 participated in lung cancer progression and functioned as a diagnostic biomarker and therapeutic target." (PMID 34421359, 2021). "First, the A/A homozygous genotype of rs217727 SNP in the H19 was significantly associated with an increased lung cancer risk (odds ratio (OR) = 1.661, 95% confidence interval (CI) = 1.155 to 2.388, P = 0.006)." (PMID 32272875, 2020). "The results of a study showed that lncRNA H19 acted as an oncogenic gene in lung cancer, and lncRNA H19 overexpression was found to be associated with the poor survival in lung cancer patients." (PMID 31217928, 2019). "Their results gave some indication that AA genotype of rs217727 SNP in lncRNA H19 gene plays a positive role in susceptibility to lung cancer." (PMID 31772668, 2019). "Many studies had shown that lncRNAs are associated with lung cancer, such as H19, ATB, CDKN2B-AS1, and MALAT1." (PMID 31775885, 2019). "Only one recent case–control study reported another SNP rs2107425 of H19 promoter region showed a combined greater impact on affecting lung cancer risk than individual effects of the SNPs with cooking smoke exposure." (PMID 31452627, 2019). "Accumulating evidence suggests that loss of imprinting and deregulation of the H19 gene are associated with human cancer, and its overexpression is a frequent event in lung cancer development." (PMID 30071841, 2018). "This study assessed the association between H19 genetic polymorphisms and the susceptibility of lung cancer." (PMID 30219045, 2018). "We further explore the combined effects of H19 SNPs and cooking oil fume exposure on lung cancer risk." (PMID 30219045, 2018). "We found that H19 rs2107425 and rs2839698 were associated with severe gastrointestinal toxicity, and rs2839698 in lung cancer patients with severe hematologic toxicity have accepted GP regimen." (PMID 30219045, 2018). "In the present study, we selected four common SNPs (rs217727, rs2107425, rs2735469, and rs17658052) in H19 gene to estimate the association between these variants and lung cancer susceptibility." (PMID 30219045, 2018). "In the present study, the association between H19 polymorphisms and lung cancer susceptibility was analyzed based on our previous GWAS results." (PMID 30219045, 2018). "The report also showed that there was a significant association between overexpression of H19 and the poor survival of lung cancer patients." (PMID 30219045, 2018). "The case-control study was conducted to evaluate the association between four selected single nucleotide polymorphisms (rs217727, rs2107425, rs2735469 and rs17658052) in H19 gene and the risk of lung cancer." (PMID 30219045, 2018). "The loss of imprinting of IGF2 and H19 from parental alleles were previously linked to cervical cancer; Loss of imprinting of H19 was also linked to lung cancer and hepatoblastoma." (PMID 28198667, 2017). "Over-expression of H19 lncRNA has been been reported to accompany the up-regulation of a 95 kDa membrane glycoprotein (p95) observed in variants of breast and lung carcinomas that are multi-drug resistant." (PMID 26623562, 2016).
lung carcinoma (continued). "This has been further strengthened by the fact that increased expression of mdig/MINA as well as H19 has been associated with the poorer survival of patients suffering from lung cancer." (PMID 26413213, 2015). "These authors also found a strong association between c-MYC and H19 transcript levels, in both primary breast and lung cancer patient material." (PMID 25593996, 2014). "Additional lncRNAs whose expression has been shown to be deregulated in lung carcinoma include H19, which undergoes loss of imprinting and overexpression, MALAT-1, cancer up-regulated drug resistant (CUDR), and BC200." (PMID 22852089, 2012). "Notably, the heightened expression of H19 lncRNA, observed in numerous adult malignant lung cancer tumours, has been linked to NSUN2‐mediated m5C modification, resulting in H19 stabilisation and subsequent pro‐oncogenic effects." (PMID 40008496, 2025). "H19 single nucleotide polymorphisms (SNPs) were significantly associated with both responsiveness to platinum-based chemotherapy and the risk of developing lung cancer." (PMID 39912974, 2025). "Furthermore, the involvement of the lncRNA H19/miR-19b-3p/FTH1 axis in curcumenol's ferroptotic effects suggests a specific molecular mechanism underlying its impact on lung cancer cells." (PMID 39104501, 2024). "In addition, single-nucleotide polymorphisms (SNPs) in the lncRNA H19 were found to be associated with susceptibility to lung cancer, especially NSCLC." (PMID 34863180, 2021). "In addition, the T/T genotype of LncRNA H19 SNP rs217727 had a higher risk of lung cancer development than those of C/C genotype." (PMID 33799753, 2021). "The long non-coding RNA, H19, has been linked to many carcinomas, including lung cancer." (PMID 32512929, 2020). "Additionally, a nucleotide polymorphism, the H19-rs217727 C>T, was found significantly associated with an increased risk of lung cancer." (PMID 32438606, 2020). "Consequently, with further efforts to confirm these results in large independent cohorts, H19 would make a great biomarker to diagnose or to assess a genetic predisposition to lung cancers." (PMID 32438606, 2020). "In the present study, so as to obtain some clues about the biological role that the gene-environment interaction played in the development of lung cancer, the interaction of both lncRNA H19 SNPs and cooking oil fume with the susceptibility of lung cancer was evaluated." (PMID 30219045, 2018). "In summary, this study showed that the single nucleotide polymorphisms in H19 gene might play vital roles in lung cancer development." (PMID 30219045, 2018). "It was revealed that H19 lncRNA is over-expressed in lung cancer due to the loss of imprinting." (PMID 25884481, 2015). "Another example is the association between lncRNA H19 and lung cancer." (PMID 26061969, 2015). "Whether H19 and miR-675 are secreted in the exosomes/body fluids and can be used as diagnostic as well as prognostic tools in lung cancer patients needs to be elucidated." (PMID 25884481, 2015). "Its downregulation has been shown to decrease breast and lung cancer cell clonogenicity and anchorage-independent growth, whereas the loss of imprinting at the H19 locus, and resulting overexpression, has been described in many other cancers, including esophagus, colon, liver and bladder." (PMID 25593996, 2014).